CD4 (CD4 molecule)
Diseases named in the same sentence as CD4 in open-access papers (continued):
Sharing a sentence is not in itself a finding about the gene and the disease.
AIDS (continued). "We described sociodemographic characteristics, the proportion of MOHD, and advanced HIV defined as baseline CD4 < 200 cells or an AIDS defining condition." (PMID 41853253, 2026). "Toxoplasmic encephalitis (TE) is a severe and potentially life-threatening manifestation that presents as an opportunistic infection in AIDS patients with low CD4 counts." (PMID 41246707, 2025). "Mortality remains significantly higher among those with lower CD4+ T cell counts (<350 cells/μL) and those presenting with AIDS at enrollment, with relative risks of 2.50 and 2.22, respectively, compared to those without such conditions." (PMID 40799781, 2025). "Herpes vegetans (HV) is an uncommon HSV infection seen in patients who are immunocompromised, such as those with human immunodeficiency virus (HIV) or acquired immunodeficiency syndrome (AIDS) with very low CD4+ lymphocyte cell counts (<50 cells/mm3)." (PMID 41189832, 2025). "These individuals typically presented with a CD4+ T cell count of less than 200 cells/mm3 and/or a history of AIDS-defining illness." (PMID 40709192, 2025). "Under certain conditions, such as viral infections, AIDs, and different cancers, upon activation, CD4+ helper T cells also act as killer T cells known as CD4+ CTLs." (PMID 41009359, 2025). "Infection progresses through acute HIV (2–4 weeks post-exposure, with fever, rash, and lymphadenopathy), chronic latency (often asymptomatic), and AIDS, which is defined by CD4+ < 200 cells/μL or AIDS-defining illnesses." (PMID 41303393, 2025). "Research indicates that HIV/AIDS patients with a CD4+ T cell count below 100/μL often suffer from ongoing diarrhea." (PMID 40557273, 2025). "The mean age was 41 years, with a median CD4+ count of 431 cells/μL; 12.4% were in the AIDS stage, and 21.5% had a detectable viral load." (PMID 41295589, 2025). "Ninety (38.1%) individuals presented with a CD4 cell count <200 cell/mm3 and 64 (27.1%) with an AIDS-defining condition and 30 (12.7%) with an HIV-RNA count >500,000 cp/ml." (PMID 40176857, 2025). "Understanding the factors associated with and testing practice among those with late (CD4 < 350 cells/μL) and advanced diagnoses (CD4 < 200 cells/μL) is essential to diminish AIDS‐related morbidity and mortality." (PMID 40464595, 2025). "Late HIV diagnosis is defined as presenting for care with a CD4 count <350 cells/μl or an AIDS-defining event, and it continues to be a significant challenge in the global effort to prevent and control HIV/AIDS." (PMID 40469732, 2025). "This is particularly evident in patients with AIDS who exhibit CD4+ T cells <100 cells/μL and HIV RNA >100,000 copies/mL, as they are more likely to develop CMVD." (PMID 39773065, 2025). "HIV/AIDS patients often present with reduced immunity due to reduction of CD4+ cells over time, thus exposing the patients to opportunistic infections by bacteria, fungi, viruses and parasites." (PMID 39879160, 2025). "In the early stages of infection, 10–15 % of HIV-1-infected individuals have a quick decline in CD4+ T-cell count, which quickly progresses to AIDS." (PMID 40296890, 2025). "Average lifetime Nadir CD4+ T-cell count was 282.0 ± 195.1 (range = 3–800), and 44.2% (n = 38/86) had been diagnosed with acquired immunodeficiency syndrome (AIDS) in their lifetime." (PMID 40872856, 2025). "Studies have found that high HIV viremia and low CD4+ T cell counts are associated with poor prognosis in COVID-19, with a higher risk of adverse outcomes in HIV/AIDS patients with a CD4+ T cell count below 200 cells/μL and those who have not received ART." (PMID 39858912, 2025). "Studies conducted in both pathogenic and non-pathogenic models of SIV infection demonstrated a direct correlation between progression to AIDS and levels of CD4 T cell apoptosis." (PMID 39997464, 2025). "Infectious workup revealed a new diagnosis of AIDS with a viral load of 1,070,000 copies/mL and a CD4 count of 13 cells/μL." (PMID 41262801, 2025).
AIDS (continued). "Late diagnosis is defined as a CD4+ T cell count < 350 cells/mm3 or an AIDS-defining event within 6 months of HIV diagnosis, unless there is evidence of recent infection." (PMID 41311323, 2025). "Deconvolution analysis using CIBERSORTx in GSE29429 revealed significant differences in the composition of different CD4+ T cell subtypes between AIDS and healthy samples." (PMID 40331958, 2025). "Seven had risk factors for mycobacterial infection, including two from endemic regions, one on adalimumab, a lung transplant recipient, and three with AIDS (CD4 < 50)." (PMID 40697884, 2025). "The HSA-CD4 fusion showed inhibitory activity on AIDS virus entry into CD4+ cells, more effectively than CD4 by itself." (PMID 41020890, 2025). "As the disease progresses from clinical latency to acquired immunodeficiency syndrome (AIDS), CD4+ T cells depletion continues to be the primary indicator of HIV infection." (PMID 41463453, 2025). "Our aim was to evaluate long-term health-related quality of life (HRQoL) in 253 people living with HIV (PLH) from the CoRIS cohort presenting to care with advanced HIV disease (AIDS or CD4 ≤ 100 cells/μL) and who had survived ≥ 5 years." (PMID 40369301, 2025). "In terms of the mean CD4 count at their first visit to the AIDS clinics, CRF07_BC patients had significantly lower number of CD4 count than the other two cohorts (p < 0.001)." (PMID 40460167, 2025). "In HIV infection, the activation of MLKL by RIPK3 is a critical step in the necroptosis of CD4+ T cells, contributing to the immunodeficiency characteristic of AIDS." (PMID 40072080, 2025). "The CD4 lymphocyte count in individuals with HIV serves as a key indicator of disease progression and the risk of death from AIDS." (PMID 40566275, 2025). "Among people living with HIV, 76.9% (n = 10) had acquired immunodeficiency syndrome (AIDS, CD4 < 200/mm3)." (PMID 41267039, 2025). "AIDS/VL and VL subjects had similar higher expression of activation markers, in both CD4+ and in CD8+ T cells." (PMID 40096173, 2025). "The relatively low CD4 counts (median of 286 cells/mm3) and the AIDS-defining conditions upon referral to the PPP are alarming." (PMID 41472237, 2025). "This reflects the progression of HIV infection, ultimately leading to the AIDS state characterized by the complete depletion of CD4+ T cells." (PMID 40431602, 2025). "This is particularly the case for individuals with advanced HIV/AIDS (with a CD4 count of less than 50 cells/μl), those undergoing chemotherapy, or organ transplant recipients." (PMID 40176807, 2025). "Despite documented increases in ART coverage over the last decade, advanced HIV disease/AIDS (CD4 <200 cells/μL) and opportunistic infections are still a major problem in sub-Saharan Africa." (PMID 41040645, 2025). "All adults hospitalized for advanced HIV disease (CD4 count <200 cells/μL or with AIDS-defining events) at a tertiary center in Mexico City between January 2015 and December 2022 were included." (PMID 40176257, 2025). "Older age, males, lower educational attainment, homosexual contact, injection of drugs, and lower baseline CD4 levels are influential factors for shorter survival time in HIV/AIDS patients receiving ART." (PMID 41048256, 2025). "Due to the low number of events, it was not possible to analyze the correlation between seroprevalences and factors such as nadir CD4+ T cell count, previous AIDS-defining events, sex, and immigration status." (PMID 41150371, 2025). "We report two cases of lupus vulgaris in AIDS patients (CD4 count of 113 cells/mm3 and 172 cells/mm3, respectively) and one case of mucosal TB in a patient with CD4 count of 365 cells/mm3." (PMID 40385314, 2025). "Chronic inflammation, driven by these cytokines, is strongly associated with several negative outcomes and is ultimately associated with the clinical progression of HIV, including poor CD4+ T cell recovery and the onset of non-AIDS-related comorbidities." (PMID 40704918, 2025).
AIDS (continued). "Antiretroviral therapy (ART) is essential to reduce viral load and restore CD4+ T cell levels in people living with HIV/AIDS (PLWHA)." (PMID 40367013, 2025). "Almost half of participants (45.9%) had an AIDS diagnosis, and all had CD4 levels below 100 cells/μL at inclusion." (PMID 40369301, 2025). "The commonality between the two patients with Lupus vulgaris was that both had defaulted ARV treatment and both had AIDS, as defined by low CD4 counts." (PMID 40385314, 2025). "In a study by Esbjörnsson and colleagues, individuals who were infected with HIV-2 prior to HIV-1 had the longest time-to-AIDS and maintained the highest CD4+ T-cell counts." (PMID 40687432, 2025). "Chronic HIV-1 infection results in the steady decline of CD4+ T cells and the development of acquired immunodeficiency syndrome (AIDS), a deadly disease that has already killed more than 42 million people worldwide." (PMID 40202316, 2025). "Esophageal candidiasis (EC) most commonly occurs in patients with human immunodeficiency virus (HIV) in the AIDS stage (CD4+ counts < 100 cells/ml)." (PMID 40104486, 2025). "The virus steadily decreases the amount of CD4+ T cells in patients, impairing the immune system and finally leading to acquired immunodeficiency syndrome (AIDS)." (PMID 40296890, 2025). "High-efficacy antiretroviral treatment (ART) has been a game-changer for HIV/AIDS pandemic, but incomplete CD4+ T cell recovery and persistent chronic immune activation still affect HIV-suppressed people." (PMID 39842407, 2025). "The groups had a similar estimated duration of HIV infection, and although about two-thirds of participants carried an AIDS diagnosis, the median CD4+ T-cell count was >500 cells/μL at the time of inclusion." (PMID 40573339, 2025). "The human immunodeficiency virus (HIV) targets the body's immune system, particularly CD4+ T-cells, and progresses to AIDS if untreated." (PMID 40458538, 2025). "HIV is a retrovirus that targets the immune system, specifically CD4+ T cells, leading to a decline in immune function that can result in the development of AIDS." (PMID 39918304, 2025). "Health facility ART provider and HIV/AIDS program manager should give special attention for clients with history of TB co-infection and CD4 count < 200 needs care and support and providing TB preventive therapy." (PMID 40740356, 2025). "HIV/AIDS is an immunosuppressive disease that targets the immune system of the body through the invasion and destruction of CD4+ cells, a clone of T-lymphocytes white blood cells that play an important role in immune responses." (PMID 39879160, 2025). "The magnitude of the association was attenuated in the alternative model adjusting for comorbidities and AIDS [aHR 1.57, 95% CI 1.00–2.48, P = .052] and lost after adjusting also for baseline CD4 cell count [aHR .93, 95% CI .57–1.53, P = .783]." (PMID 40749106, 2025). "As with all live vaccines, MMR vaccination is contraindicated in HIV infection with CD4 percentage <15% or CD4 count < 200 cells/mm3 and/or AIDS." (PMID 40872885, 2025). "In PWH off ART, with AIDS, or low CD4 T cell count, an expansion of phages and other NHV has been described in the blood." (PMID 40060671, 2025). "It is contraindicated in individuals with CD4 cell counts < 200/μL (14%) and/or AIDS, as well as in individuals with a history of/or current hematological neoplasia or thymus-related conditions (such as thymoma, resection, or radiation)." (PMID 40872885, 2025). "Accurately counting CD4+ T lymphocytes is crucial for managing HIV/AIDS, especially in resource-limited settings where access to advanced diagnostic facilities is scarce." (PMID 39852084, 2025). "In order to investigate the potential of anti-CD4 mAb on ADCC, a culture was set up with NK cells (peripheral blood of healthy volunteers) and CD4 + T cells (peripheral blood of AIDS patients), using IgG or PBS as controls." (PMID 40542350, 2025).
AIDS (continued). "The HIV group showed significantly lower proportions of senescent CD4+T cells than Asympt HIV/Leish or AIDS/VL subjects." (PMID 40096173, 2025). "This population, characterized by high CD4+ T cell counts and a low incidence of opportunistic infections, provides an optimal model for examining non-AIDS comorbidities, with cardiovascular disease emerging as a primary concern." (PMID 40718411, 2025). "Other data from the eHARS and DC Cohort for this project include demographics, opportunistic infection history, dates of HIV and AIDS diagnoses, CD4 counts and percentages, and viral loads." (PMID 40811829, 2025). "HIV-1 can eventually escape immune control, and the CD4+ T cell count will slowly but steadily decrease below 200 CD4 T cells/μL (the threshold definitive of AIDS), establishing the final AIDS phase, which can take from months to several years to develop." (PMID 41373539, 2025). "Nonetheless, once better immunity is reached with a high CD4 count, the disease course is often much more indolent than during the AIDS stage, with a low CD4 count." (PMID 40119751, 2025). "There are 220,000 annually reported cryptococcal meningitis in advanced AIDS (at a CD4 cell count under 100/mm3) globally and 33% annually reactivations of cerebral toxoplasmosis in advanced AIDS patients (at a CD4 count below 50–100/mm3)." (PMID 40142374, 2025). "Baseline CD4 at first presentation was obtained from the national integrated AIDS prevention and control information system." (PMID 41454047, 2025). "Median baseline CD4+ lymphocyte count was 488 cells/mm3, 21 subjects (36.2%) had a CD4+ lymphocyte count <350 cells/mm3, and 5 (8.6%) subjects had AIDS diagnosis." (PMID 39806529, 2025). "In the present study, all patients with AIDS had a CD4 cell count of <200/μL, except for one patient, with half of the patients (five cases) exhibiting a count of <50/μL, which is associated with a substantially increased risk of opportunistic infection." (PMID 40356617, 2025). "In clinical practice, AIDS patients with low CD4+ T cell counts should be screened for CMV infection." (PMID 39773065, 2025). "Compared to nonprecarious PHIV, they presented more frequently with a history of AIDS-defining conditions and, despite similar cART exposure, a lower baseline CD4 cell count and a lesser rate of viral suppression." (PMID 41322243, 2025). "Wu and colleagues demonstrated the inhibitory activity of TRIM5α against HIV-2, which was characterized by increased CD4+ T-cells and longer AIDS-free survival." (PMID 40687432, 2025). "The persistence of HIV-1 in transcriptionally silent latent form in long-living memory CD4+ T cells is one of the main barriers to a cure of HIV/AIDS." (PMID 41038866, 2025). "In patients without antiretroviral therapy (ART), it takes approximately 12-18 months to develop an AIDS-defining condition once the CD4 cell count is less than 200 cells/microL." (PMID 39958093, 2025). "HIV specifically targets and depletes CD4+ T cells, leading to acquired immunodeficiency syndrome (AIDS) after an initial asymptomatic period during which the virus replicates at low levels." (PMID 40370442, 2025). "A 33-year-old Colombian male patient with HIV/AIDS diagnosis, characterized by a CD4 cell count of 28 cells/mm3 and a plasma HIV RNA level of 566.357 copies/mL, started antiretroviral therapy (ART) with zidovudine combined with lamivudine and efavirenz." (PMID 39897288, 2025). "This case describes a newly diagnosed AIDS patient with severe CD4+ depletion who presented with seizures and encephalopathy and was ultimately found to have VZV and EBV coinfection of the CNS." (PMID 40959339, 2025). "Studies conducted on human cells have demonstrated that fractionated acetone water neem leaf extract effectively prevents the invasion of HIV‐1 and leads to a notable increase in CD4+ cell counts in a limited number of HIV/AIDS patients." (PMID 40901661, 2025).
AIDS (continued). "Thresholds such as CD4 ≤200 cells/mm3 (indicating AIDS) are critical for decision-making, while thresholds of ≤350 cells/mm3 reflect evidence supporting earlier intervention." (PMID 39852084, 2025). "Both men were in the AIDS stage at the time of the dermatologic visit (CD4+ T cell < 200 cells/mm3) and received a histological diagnosis of KS, as expected." (PMID 41010651, 2025). "A reduced CD4/CD8 ratio reflects immune dysregulation and increased systemic inflammation and is associated with a greater risk of AIDS-defining conditions and all-cause mortality." (PMID 40950964, 2025). "In this retrospective cohort study, we analyzed people living with HIV/AIDS whose demographic data, CD4+ T lymphocyte count, and viral load." (PMID 40809772, 2025). "In HIV/AIDS, severe CD4+ T-cell depletion (<50 cells/μL) further cripples EBV-specific immunity, enabling uncontrolled viral replication and molecular mimicry between EBV nuclear antigens (e.g., EBNA-1) and erythrocyte surface proteins (e.g., Band 3)." (PMID 40843879, 2025). "Subjects with AIDS/VL had more CD3+CD4+CD38+HLA-DR+ activated T cells when compared to recovered VL (p = 0.0004), HIV (p = 0.0001), and DTH+ (p<0.0001)." (PMID 40096173, 2025). "Asympt HIV/Leish and AIDS/VL subjects had similar proportions of T cells expressing activation markers in CD4+ or CD8+ T cells." (PMID 40096173, 2025). "Our case differs significantly as the patient had newly diagnosed AIDS with profound immunosuppression (CD4 count 16/μL), which likely contributed to both prolonged viral shedding and poor outcome." (PMID 41155576, 2025). "The virus targets CD4-positive T cells, progressively impairing immune function and potentially advancing to acquired immunodeficiency syndrome (AIDS) if left untreated." (PMID 41035583, 2025). "C. neoformans is associated with meningitis in immunocompromised individuals, particularly those with an HIV infection who have progressed to AIDS with a CD4 count below 100 cell/mL." (PMID 41541964, 2025). "Infection and depletion of CD4+ T cells by HIV-1 are central to viral pathogenesis and the hallmark of AIDS progression." (PMID 40911682, 2025). "Limitations of the study include the exclusion of patients with low CD4+ counts, which restricted sample selection and prevented the inclusion of individuals with the most severe form of infection (AIDS)." (PMID 40367013, 2025). "Esophageal candidiasis (EC) occurs more commonly in patients with human immunodeficiency virus (HIV) in the AIDS stage (CD4+ counts < 100 cells/ml)." (PMID 40104486, 2025). "AIDS is a severe medical condition caused by the human immunodeficiency virus (HIV) that primarily attacks the immune system, specifically CD4+ T lymphocytes (a type of white blood cell crucial for immune response), monocyte macrophages, and dendritic cells." (PMID 40066012, 2025). "HIV is a virus that weakens the immune system by attacking white blood cells, specifically CD4+ lymphocytes, and AIDS is the most advanced disease stage, defined by CD4+ cell counts less than 200 cells/mm3." (PMID 41189832, 2025). "This review focuses on the absolute CD4 count, the most commonly used metric, which measures the concentration of CD4 cells in the blood, which values below 200 cells/mm3 indicate AIDS." (PMID 39852084, 2025). "Proportions of CD4+T expressing PD1+ in AIDS/VL subjects were significantly higher than among HIV subjects." (PMID 40096173, 2025). "It is well known that HIV‐induced immune suppression plays a key role in increasing the cancer risk of PWH, particularly for virus‐related cancers, and risk has been shown to increase with low CD4 cell count, high HIV viral load, and a prior AIDS diagnosis." (PMID 40437996, 2025). "After the initiation of antimicrobial therapy, he was found to be HIV positive with confirmed AIDS, as his CD4 count was 86 cells/mm3." (PMID 40677426, 2025).